HSPA1L (heat shock protein family A (Hsp70) member 1 like)
Diseases named in the same sentence as HSPA1L in open-access papers:
HSPA1L is named in the same sentence as 60 diseases in open-access papers, as found by Europe PMC text mining. Sharing a sentence is not in itself a finding about the gene and the disease. The quoted sentences say what the papers report.
breast carcinoma (6 papers, 2010 to 2025). "HSPA1L was one of the downregulated genes after gemcitabine treatment used against breast cancer." (PMID 37719007, 2023). "We suggest that HSPA1L and HSPA2 could represent potential biomarkers to follow up the effectiveness of 17AAG in breast cancer, although the mechanism underlying this effect is still unclear." (PMID 20920318, 2010). "“....HSPA1L and HSPA2 could represent potential biomarkers to follow up the effectiveness of 17AAG in breast cancer”." (PMID 23216862, 2012).
colorectal cancer (4 papers, 2019 to 2021). A primary or metastatic malignant neoplasm that affects the colon or rectum. "In detail, the tumorigenicity of colorectal cancer cells is associated with PrPc accumulation and upregulation of heat-shock 70 kDa protein-1-like (HSPA1L), which, in turn, stabilizes the hypoxia-inducible factor-1α (HIF-1α) protein." (PMID 31618844, 2019). "A recent study showed that HSPA1L is involved in accumulating prion proteins in patients with colorectal cancer recurrence." (PMID 32971893, 2020).
diabetes (3 papers, 2010 to 2023). "Additionally, HSD11B1 and HLA-DRA linked hypertension, diabetes, and obesity; UCHL1 linked hypertension, obesity, and lung cancer; LENG8 and HSPA1L linked diabetes, obesity, and lung cancer." (PMID 36685671, 2023). "The present study demonstrates unique mechanism of albuminuria induced PTCs injury mediated by HSPA1L, and we declare that vaspin/HSPA1L pathways potentially become therapeutic targets for protecting proximal tubular cells in diabetes and obesity related kidney diseases." (PMID 33742129, 2021).
lung carcinoma (3 papers, 2020 to 2023). "Cellular CSC marker protein levels were decreased in the HSPA1L-suppressed lung cancer cells but increased in cells overexpressing HSPA1L." (PMID 32971893, 2020). "Therefore, the results herein indicate that HSPA1L is an important potential intracellular activator of IGF1Rβ Accordingly, HSPA1L may be a promising new therapeutic target for treating lung cancer." (PMID 32971893, 2020).
Obesity (3 papers, 2021 to 2023). Accumulation of substantial excess body fat. "We first demonstrated HSPA1L and vaspin complex was internalized by endocytosis process mediated by clathrin heavy chain and ameliorated the obesity-induced LMP, inflammasome activation, and autophagy failure." (PMID 33742129, 2021). "Firstly, we demonstrated a role of HSPA1L in obesity and DKD." (PMID 33742129, 2021). "Furthermore, we revealed that an overload and uptake of albumin into PTCs increased the secretion of HSPA1L into culture medium and resulted in reduced levels of intracellular HSPA1L, suggesting an interest mechanism albuminuria-induced disruption of obesity-induced organellar dysfunction in PTCs." (PMID 33742129, 2021).
colon cancer (2 papers, 2020 to 2022). "Under hypoxic conditions, PrPC leads to cancer progression in colon cancer by targeting the HSP 70 member 1-like (HSPA1L)/HIF-1α/glycoprotein 78 (GP78) axis." (PMID 35885540, 2022). "For C7 (CD8+ TEMRA/TEFF), there were 359 DEGs between colon cancer and rectal cancer, such as HSPA1L and IL7R were up-regulated, while CD8A and CTSW were down-regulated in colon cancer compared to that in rectal cancer." (PMID 33584715, 2020).
diabetic kidney disease (2 papers, 2021 to 2025). Progressive kidney disorder caused by vascular damage to the glomerular capillaries, in patients with diabetes mellitus. "In proximal tubular kidney cells (PTCs), nucleus-specific HSP70 isoform HSPA1L plays a similar function, protecting cells from diabetic kidney disease (DKD)." (PMID 41372524, 2025).
Hearing impairment (2 papers, 2017 to 2021). A decreased magnitude of the sensory perception of sound. "Different haplotypes of HSPA1L/HSPA1A/HSPA1B SNP combinations were associated with variable etiologies of hearing impairment." (PMID 33926545, 2021). "In our earlier studies on the associations of HSP70 genetic polymorphisms (HSPA1L/HSPA1A/HSPA1B: rs2075800/rs1043618/rs2763979) with NIHL and sudden sensorineural hearing loss (SSNHL), different haplotypes were associated with diverse risks of these hearing impairments." (PMID 33926545, 2021).
infertile (2 papers, 2015 to 2019). "In fact, overexpression of 5 HSPs and 5 CCTs is noticed in High ROS infertile group whereas only one HSP each, HSPA1L and HSP90AA1 was induced in Medium and Low ROS group respectively." (PMID 26321892, 2015).
inflammatory bowel disease (2 papers, 2017 to 2018). A spectrum of small and large bowel inflammatory diseases of unknown etiology. "In agreement with our findings, a previous study of Caucasian patients with inflammatory bowel disease found that rare mutations in HSPA1L were significantly enriched in patients but absent in healthy controls." (PMID 30001343, 2018).
paranoid schizophrenia (2 papers, 2020 to 2022). "In our previous work, we explored the possibility that HSPA1A (+190G/C), HSPA1B (+1267A/G), and HSPA1L (+2437T/C) gene polymorphisms might be involved in the susceptibility to paranoid schizophrenia and clinical presentation of the disease in the Polish population." (PMID 31642026, 2020). "The genes encoding HSPA1A, HSPA1B, and HSPA1L are located in the MHC class III region of 6p21.3–22.1, which is a region implicated in susceptibility to schizophrenia." (PMID 35562887, 2022).
preeclampsia (2 papers, 2018 to 2020). Preeclampsia is a hypertensive disorder of pregnancy that is characterized by new-onset hypertension with proteinuria presenting after 20 weeks of gestation, and depending on mild or severe forms may initially present with severe headache, visual disturbances, and hyperreflexia. "Although, studies of the role of HSPA1L and HSPA1L in pregnancy are lacking, there is some evidence of involvement in adverse pregnancy outcomes such as preeclampsia." (PMID 30001343, 2018).
atopic dermatitis (1 paper, 2024). "For example, AIF1, MICA, ATF6B, and HSPA1L were found to be associated with an increased risk of rheumatoid arthritis (RA), while AIF1 was also associated with an increased risk of atopic dermatitis." (PMID 38835753, 2024).
chronic kidney disease (1 paper, 2021). Impairment of the renal function secondary to chronic kidney damage persisting for three or more months. "Specifically, we are planning to measure of human urinary HSPA1L in patients with acute or chronic kidney diseases including DKD and demonstrate a clinical significance of HSPA1L." (PMID 33742129, 2021).
COVID-19 (1 paper, 2021). A disease caused by infection with severe acute respiratory syndrome coronavirus 2. "The methylation level of HSPA1L was significantly decreased and the mRNA expression was increased in both asymptomatic and severe COVID-19 blood samples suggesting its epigenetic regulation by SARS-CoV-2 infection." (PMID 33679887, 2021). "In conclusion, for the first time, we have shown that compared to healthy individuals the HSPA1L was highly expressed in lung biopsies of patients with severe COVID-19 and lung epithelial cells infected with SARS-CoV-2." (PMID 33679887, 2021). "The level of HSPA1L expression was found to be significantly increased in COVID-19 lung biopsies and infected epithelial cells." (PMID 33679887, 2021). "We found that HSPA1L gene is hypomethylated and overexpressed in COVID-19 patients." (PMID 33679887, 2021). "The similar function of the HSPA1L gene could be attributed to COVID-19 lungs, suggesting that SARS-CoV-2 infected cells epigenetically upregulated the HSPA1L gene, hence Hsp70 proteins, to facilitate coronavirus replication in these host cells." (PMID 33679887, 2021). "For the HSPA1L gene, the promoter methylation level was significantly lower (hypomethylation) and the mRNA expression was significantly higher in both asymptomatic and symptomatic COVID-19 compared to healthy controls." (PMID 33679887, 2021).
ischemia (1 paper, 2020). A hypoperfusion of the BLOOD through an organ or tissue caused by a PATHOLOGIC CONSTRICTION or obstruction of its BLOOD VESSELS, or an absence of BLOOD CIRCULATION. "Like these preclinical studies, we have shown that melatonin‐treated senescent MSCs enhance functional recovery in a murine hindlimb ischemia model by inhibiting apoptosis, increasing proliferation, and augmenting neovascularization via HSPA1L expression." (PMID 31965731, 2020).
leukemia (1 paper, 2018). A malignant (clonal) hematologic disorder, involving hematopoietic stem cells and characterized by the presence of primitive or atypical myeloid or lymphoid cells in the bone marrow and the blood. "Next, we performed WES of five Sca1‐Lmo2 + nu/nu mice with leukemia and observed 14 somatic alterations (SNVs) in Cdh11 (1/5), Cd1d1 (2/5), Sept6 (2/5), and Hspa1l (1/5; Table EV1)." (PMID 29880602, 2018).
liver failure (1 paper, 2018). A liver disease characterized by the liver losing or has lost all of its function. "Liver failure or one factor of complications documented by Denver multiple organ failure scores was associated with HSPA1L genotype CT." (PMID 30060485, 2018).
mastitis (1 paper, 2025). Inflammation of breast tissue during lactation or postpartum due to an obstructed duct or infection. "It is worth noting that the upregulation of HSPA1A/HSPA1L after CK666 treatment emphasizes a compensatory cytoprotective response that may be an adjuvant treatment strategy for mastitis." (PMID 40305275, 2025).
myopia (1 paper, 2024). "With the comparisons of positive rates of each autoantibody between emmetropia and high myopia groups, a total of 18 autoantibodies, including anti-ZNF48, anti-HSPA1L, etc. were identified as high myopia-related candidate autoantibodies (Fisher’s exact test, all p < 0.05)." (PMID 38729610, 2024).
neuroblastoma (1 paper, 2023). Neuroblastoma (NB) is the most common solid, extracranial childhood tumor. "HSPA1L specifically overexpresses only in neuroblastoma SH-SY5Y and differentiates SH-SY5Y cells at 2.5–3.5-fold, with a relatively higher value in the case of later." (PMID 36979108, 2023).
uterine corpus endometrial carcinoma (1 paper, 2021). A endometrial carcinoma (disease) that involves the body of uterus. "HSPA1L mRNA was down-regulated in uterine corpus endometrial carcinoma." (PMID 34712697, 2021).
viral infections (1 paper, 2023). "HSPA2 and HSPA1L do not show clear changes in other viral infections or HIV-1 infections, because they are enriched in testicular tissue, which may play vital roles in the process of HIV-1 invasion." (PMID 36845091, 2023).
vitiligo (1 paper, 2024). Generalized well circumscribed patches of leukoderma that are generally distributed over symmetric body locations and is due to autoimmune destruction of melanocytes. "By contrast, HSPA1L T/C is associated with protection against vitiligo." (PMID 38438962, 2024).
cancer (14 papers, 2012 to 2023). A tumor composed of atypical neoplastic, often pleomorphic cells that invade other tissues. "HSPA1L/integrin αV complex-associated IGF1Rβ activation intensified the EMT-associated cancer stemness and γ-radiation resistance through its downstream AKT/NF-κB or AKT/GSK3β/β-catenin activation pathway." (PMID 32971893, 2020). "For example, in the HSP70 family, HSPA5 and HSPA6 were positively associated with the hypoxia score in 23 and 20 cancers, respectively, while HSPA1L was negatively associated with hypoxia in 19 cancers." (PMID 33225964, 2020). "Despite continued reports that HSPA1L polymorphisms are closely associated with various diseases, little is known about the specific signaling or mechanism by which HSPA1L functions in cancer cell stemness." (PMID 32971893, 2020). "Moreover, despite reports that genetic variations of HSPA1L may be linked to cancer, the pathways and mechanisms by which HSPA1L is involved in cancer stemness and poor prognoses are unclear." (PMID 32971893, 2020). "Although HSPA1L’s importance in cancer proteostasis is coming to the fore, HSPA1L is otherwise primarily a testes-specific chaperone." (PMID 36979108, 2023). "HSPA1L is one of the most recognized cancer-related chaperones, modulating multiple biological processes in various cancers." (PMID 34905506, 2021). "Evidence showed that HSPA1L can enhance cancer stem cell-like properties via regulating β-Catenin transcription and activating IGF1Rβ." (PMID 34412642, 2021). "For example, in the HSP70 family, HSPA4 positively correlated with cell proliferation in 14 cancer types, while HSPA1L negatively correlated with cell proliferation in 14 cancer types." (PMID 33225964, 2020). "Inhibiting HSPA1L expression with siRNA in A549 and H460 cells significantly reduced the cancer cell mobility and invasiveness." (PMID 32971893, 2020). "Although many HSP functions have been identified, little is known about the function of the HSPA1L in cancer cells." (PMID 32971893, 2020). "Thus, HSPA1L enhanced CSC-like properties in cancer cells by both activating IGF1Rβ and regulating β-catenin transcription." (PMID 32971893, 2020). "Therefore, HSPA1L is closely related to IGF1Rβ activation and consequently activates its downstream signals to promote cell proliferation and malignant cancer cell progression." (PMID 32971893, 2020). "Thus, HSPA1L can partially enhance stemness of cancer cell via direct or indirect regulation of the β-catenin/ALDH1 axis." (PMID 32971893, 2020). "HSPA1L may be a novel potential target for cancer treatment because it both enhances IGF1Rβ activation and regulates γβ-catenin transcription, accumulating CSC-like properties." (PMID 32971893, 2020). "Interestingly, our study showed that cancer cells of the marsupial Tasmanian devil upregulate HSPA1L after heat shock." (PMID 29702669, 2018). "Additionally, HSPA1L binds to OCT4 in cancer stem cells, resulting in maintenance of stemness." (PMID 31965731, 2020). "HSPA1L also partly affected stemness and EMT in cancer cells by regulating ALDH1 expression via β-catenin stabilization by the IGF1Rβ/AKT/GSK3β activation pathway." (PMID 32971893, 2020). "In these networks, PTGS2, VDR, RHOB, PIM1, HSPA1L, HSPA1A, and SPHK1 were used as targets for cancer drug development, previously." (PMID 30842898, 2019). "We counted the numbers of pathways affected by each HSP; the results suggested that HSPA1L, HSPA12B, HSPA6, HSPA7 and HSPA12A may influence the activity of most cancer-related pathways and thus potently affect tumor development." (PMID 34712697, 2021). "In this study, we confirmed for the first time that HSPA1L was highly expressed in ALDH1high CSC-like cells isolated from an NSCLC cell line and was involved in stemness and γ-radiation resistance of cancer cells by activating IGF1Rβ and regulating β-catenin transcription." (PMID 32971893, 2020). "However, it is not even known whether HSPA1L exists in the nucleus of cancer cells." (PMID 32971893, 2020).
tumor (10 papers, 2010 to 2025). "Under hypoxic conditions, PrPC induces tumor progression in CRC by targeting the heat shock protein 70 member 1-like (HSPA1L)/HIF-1α/GP78 signal axis." (PMID 33946823, 2021). "The mRNA expression levels of AHNAK, EMP1, RASGRP4, and HSPA1L were significantly down-regulated in BUC tumor tissues compared with normal tissues while SLC1A6 and PRSS8 were significantly up-regulated (P < 0.05)." (PMID 34905506, 2021). "Only HSPA1L showed significantly lower expression in tumor tissues in elder BUC patients compared with the younger counterparts (P = 0.021); there were no significant expressing differences for the other 5 genes." (PMID 34905506, 2021). "The heat-shock 70-kDa protein-1-like (HSPA1L) gene is pivotal in tumor niche condition-induced HIF-1α activation and cellular prion protein (PrPC) regulation and leads to CRC proliferation." (PMID 30755640, 2019). "In contrast, HSPA1L (HSP70-1L) was expressed at higher levels in skin than primary tumours and cell lines." (PMID 29702669, 2018). "One aim of this study was to determine whether HSPA1L was involved in tumor resistance to ionizing radiation, a CSC characteristic." (PMID 32971893, 2020). "Heat shock proteins, particularly HSPA8 (found in both patient groups), as well as HSPA1B and HSPA1L, were found in LRPCa, reflecting the role of the HSP70 family in tumor cell survival." (PMID 40136513, 2025). "The up-regulated genes following treatment included heat shock family proteins such as HSP90AA1, HSPA8, DNAJB12, HSPA1L, DNAJA1, HSPA4L, consistently with other array studies in different tumor cell types." (PMID 20920318, 2010). "Previous research has established that heat shock 70-kDa protein 1-like (HSPA1L) is crucial in promoting CRC proliferation via HIF-1α activation and cellular prion protein (PrPC) regulation within tumor niches, and its expression has already been linked to CRC prognosis." (PMID 39886381, 2025).
infection (5 papers, 2016 to 2025). The state of being infected such as from the introduction of a foreign agent such as serum, vaccine, antigenic substance or organism. "This raises an important question: could IAV evolve compensatory mutations under selective pressure from HSPA1L to escape host defenses and achieve multi-host infection?" (PMID 40788012, 2025). "In contrast, as demonstrated in this study, HSPA1L functions in a more targeted manner by directly detecting an IAV “danger” signal and limiting infection in a highly specific way." (PMID 40788012, 2025). "This fluctuation contrasts with certain HSP70 isoforms, where several are upregulated (e.g., HSPA1L, HSPA2, HSPA5, HSPA9, HSPA12, and HSPA13), while others from the HSP70 family are downregulated post-peak infection phase (Chand, Iyer & Mitra, 2021)." (PMID 39308823, 2024).
HSPA1L also shares sentences with these, for which no sentence is quoted: kidney diseases (2 papers); melanoma (2); adenocarcinoma (1); cognitive defect (1); colon adenocarcinoma (1); endometrial cancer (1); gastric cancer (1); graft versus host disease (1); Hepatitis (1); Hepatitis B (1); Hypertension (1); immunity disorders (1); keloid (1); legionellosis (1); lymph node metastases (1); malaria (1); male infertility (1); metastatic melanoma (1); Multiple Organ Failure (1); Nephropathy (1); osteosarcoma (1); pancreatic ductal adenocarcinoma (1); prion disease (1); rectal cancer (1); renal carcinoma (1); rheumatoid arthritis (1); sudden sensorineural hearing loss (1); systemic lupus erythematosus (1); triple-negative breast carcinoma (1); tuberculosis (1).
A further 3 diseases each share a sentence with HSPA1L in 1 paper.